SIRT6 (sirtuin 6)
Diseases named in the same sentence as SIRT6 in open-access papers (continued):
Sharing a sentence is not in itself a finding about the gene and the disease.
Obesity (continued). "In spite of these somewhat contradictory results, we believe that SIRT1 and SIRT6 emerge as important targets for the development of novel therapies in the control of obesity and its comorbidities." (PMID 33572672, 2021). "In fat-specific SIRT6 knockout mice fed on a high-fat diet, there was an augmented tendency to obesity, inflammation, and insulin resistance." (PMID 34389701, 2021). "Some studies indicated that the liver-specific SIRT6 expression is decreased in rats with spontaneous obesity and metabolic syndrome." (PMID 33274005, 2020). "Chrysophanol and targeted SIRT6 therapy have broad prospects for the treatment of metabolic ailments such as obesity, type 2 diabetes, and fatty liver disease." (PMID 33274005, 2020). "We recently identified myeloid Sirt6 as a key defense molecule that is required to prevent the accumulation of M1 macrophages in adipose tissue and the development of obesity and insulin resistance." (PMID 31113929, 2019). "Consistent with animal experimental data, the degree of obesity and insulin resistance demonstrated by the body mass index, fasting blood glucose and HbA1c correlated negatively with the expression of Sirt6 in human visceral fat tissues." (PMID 31113929, 2019). "Fat-specific deletion of Sirt6 increased blood glucose levels and hepatic steatosis and promoted diet-induced obesity and insulin resistance." (PMID 29535637, 2018). "We observed that liver-specific SIRT6 expression is reduced in an in vivo model of spontaneous obesity and metabolic syndrome." (PMID 30671172, 2018). "Fat-specific Sirt6 knockout not only induces obesity and insulin resistance but also impairs the thermogenic function of brown adipocytes." (PMID 30574122, 2018). "This review surveys evidence for an emerging role of Sirt6 as a regulator of metabolism in mammals and summarizes its major functions in obesity and diabetes." (PMID 29535637, 2018). "Sirt6 is a member of the sirtuin family involved in physiological and pathological processes including aging, cancer, obesity, diabetes, and energy metabolism." (PMID 30671172, 2018). "Sirt6 levels are reduced in the adipose tissue of murine models of obesity and increased in the adipose tissue of humans with weight loss." (PMID 30671172, 2018). "The activity of SIRT6 is reduced in obesity and diabetes and its hepatic-specific ablation increases liver steatosis onset." (PMID 30671172, 2018). "Diet-induced obesity was strengthened in SIRT6 knockout mice, principally attributed to hypertrophy of adipocyte other than differentiation of abnormal adipocyte." (PMID 30559718, 2018). "Downregulation of Sirt6 accelerates ROS- or high glucose-induced endothelial senescence and leads to obesity and insulin resistance." (PMID 29371988, 2017). "SIRT6, as a member of sirtuin family, has a unique biological function in lipid metabolism, thus affecting diseases such as diabetes and obesity." (PMID 28355567, 2017). "Sirt6 transgenic mice are protected from hepatic fat accumulation and pathological damage due to diet-induced obesity, and Sirt6 knockout mice show fatty liver formation and alterations in insulin sensitivity and glucose metabolism." (PMID 25133775, 2014). "In this regard, it is of interest to note that the selective ablation of SIRT6 from neurons in mice results in an adult-onset obesity, while liver-specific deletion of Sirt6 in mice results in a “fatty liver” phenotype." (PMID 25566066, 2014). "Previous results from our lab have shown SIRT6 to be involved in the calorie restriction response, and demonstrate that SIRT6 overexpression in mice protects against diet-induced obesity and its metabolic consequences." (PMID 22915706, 2012). "SIRT6 is highly expressed in the CNS and mice overexpressing SIRT6 are protected against diet-induced obesity." (PMID 22115311, 2011). "This may explain the protective role of SIRT6 in the case of metabolic consequences of diet-induced obesity." (PMID 39861104, 2025).
Obesity (continued). "SIRT1, SIRT3, and SIRT6 activation may be a new treatment strategy for various metabolic diseases including diabetes, obesity, and osteoporosis." (PMID 41304967, 2025). "Additionally, SIRT6 overexpression prevents against high‐fat diet (HFD)–induced obesity and related pathological damages, while depletion of SIRT6 in brown adipocytes inhibits thermogenesis and leads to obesity." (PMID 39971710, 2025). "Collectively, these studies demonstrate that SIRT6 acts as a protective regulator in both peripheral adipose tissue and central hypothalamic microglia, highlighting its potential as a therapeutic target for obesity and obesity-related metabolic dysfunction." (PMID 41304967, 2025). "Most studies suggest that SIRT1, SIRT3, and SIRT6 play protective roles in obesity." (PMID 41304967, 2025). "SIRT6 has emerged as a protective regulator against diet-induced obesity and metabolic syndrome." (PMID 41304967, 2025). "Sirt6 is an attractive regulatory mechanism for metabolic problemsassociated with obesity." (PMID 40622152, 2025). "In addition, we also established the obesity-driven HCC mouse model, and the Sirt6-LKO in obesity mice markedly accelerated HCC development." (PMID 38332150, 2024). "A further challenge is understanding how the increased mono-ADP ribosyl-transferase, as in SIRT6 N308K/A313S overexpression in mature adipocytes, may reflect in ameliorated glucose metabolism in the context of obesity." (PMID 39033117, 2024). "Of particular interest, some of these upstream regulators have been associated with cardiometabolic traits (though not TG), such as hypercholesterolemia, T2D, heart failure, and hyperglycemia (SIRT6); obesity (C1QTNF2); and weight gain, cardiomyopathy, liver cirrhosis, and insulin resistance (MGLL)." (PMID 39251667, 2024). "Thus, the data suggested that knockout of Sirt6 in microglia exacerbates high-fat diet-induced obesity in mice." (PMID 37582706, 2023). "Our data show that hepatic SIRT6 reduces obesity by inducing UCP1 in BAT and energy expenditure." (PMID 37566087, 2023). "Obesity, hyperglycemia, and other factors can reduce SIRT6 expression." (PMID 37876546, 2023). "The results from our study reveal that Sirt6 is involved in the regulation of M1/M2 phenotypic transition in microglia, and further confirm that hypothalamic microglia Sirt6 plays a critical role in long-term high-fat diet-induced obesity." (PMID 37582706, 2023). "For example, a paper claimed that Sirt6 inhibition exacerbates diabetic cardiomyopathy by intensifying oxidative stress and inflammation in H9c2 cell line whereas Sirt6 overexpression prevents the heart from developing obesity-mediated diabetic cardiomyopathy." (PMID 37497437, 2023). "Therefore, SIRT6 has been pursued as a promising target for prevention and treatment of human diseases, such as diabetes, obesity, inflammation, neurodegeneration, and age-related diseases." (PMID 38016059, 2023). "Our results reveal that microglia Sirt6 in the hypothalamus is essential in the regulation of metabolism and further prove that Sirt6 plays an important role in high-fat diet-induced obesity via the manipulation of hypothalamic inflammatory response and energy expenditure." (PMID 37582706, 2023). "A recent study reported that TF3 could ameliorate obesity in high-fat diet–induced mice by oral administration for 9 weeks through the signaling pathway of SIRT6/AMPK/SREBP-1/FASN." (PMID 36105184, 2022). "In contrast, SIRT2 and SIRT6 promote the occurrence and development of obesity." (PMID 36581622, 2022). "Constitutive SIRT6 deletion in myeloid cells promotes inflammation and tissue damage during obesity by promoting macrophage polarization toward an M1 phenotype, clearly showing that constitutive SIRT6 deletion in myeloid cells has deleterious effects during obesity and inflammation." (PMID 35150745, 2022). "Similarly, published data point to a reduction in SIRT6 protein levels in the AT of people with obesity." (PMID 35811457, 2022).
Obesity (continued). "Altogether, this evidence suggests that SIRT6 may be a regulator of the onset of obesity in adult rats." (PMID 33806509, 2021). "In macrophages, SIRT6 suppresses obesity-induced inflammation and insulin resistance." (PMID 34389701, 2021). "By mimicking the benefit of the IF diet regimen, activation of Sirt6 could serve as a defense against obesity and type 2 diabetes." (PMID 34493807, 2021). "Our previous studies have demonstrated that Sirt6 protects the heart from developing pressure overload hypertrophy and obesity induced diabetic cardiomyopathy, suggesting that Sirt6 may also retard the cardiac aging induced hypertrophy." (PMID 33934090, 2021). "Overexpression of SIRT6 protects mice from developing obesity and insulin resistance." (PMID 33806509, 2021). "SIRT6 plays a key regulatory role in gene transcription, metabolism, maintenance of genomic stability, and integrity of telomeres, thus regulating the occurrence and development of diabetes, obesity, heart disease, cancer, and other diseases." (PMID 33356727, 2021). "SIRT6 expression in the adipose tissue is downregulated during obesity in humans." (PMID 33806509, 2021). "Thus, Sirt6 transgenic mice are resistant to diet-induced obesity, cardiac hypertrophy and fibrosis and show improved insulin sensitivity." (PMID 32079324, 2020). "Male mice fed with a high-fat diet had impaired fertility due to obesity, along with significantly decreased SIRT6 protein and increased acetylated H3K9 and DNA damage in the nucleus, suggesting that Sirt6 might be involved in spermatogenesis." (PMID 32915773, 2020). "Altogether, our study has demonstrated that chrysophanol can inhibit lipid accumulation and prevent obesity by activating the brown adipocyte SIRT6/AMPK signaling pathway, increasing adipose decomposition, FAO, improving insulin sensitivity and thermogenesis in HFD-induced obese mice." (PMID 33274005, 2020). "Meanwhile, activation of SIRT6 may have beneficial effects on glucose and lipid metabolism in obesity and diabetes." (PMID 33274005, 2020). "Accordingly, SIRT6 is a potentially novel target to treat obesity." (PMID 33274005, 2020). "In further support of this hypothesis, we found that Sirt6 expression in visceral adipose tissue of human subjects was inversely correlated with obesity parameters and insulin resistance parameters in type 2 diabetes patients." (PMID 31113929, 2019). "In addition, adipose tissue-specific ablation of Sirt6 resulted in increased blood glucose, hepatic steatosis, and diet-induced obesity." (PMID 30671172, 2018). "Sirt6 overexpression protects against HFD-induced physiological damage by blocking the lipotoxicity of obesity and restoring glucose homeostasis via specific reduction of PPARγ signaling and level of diacylglycerol acyltransferase 1 (DGAT1), a key regulator of TG synthesis." (PMID 29535637, 2018). "Neural-specific deletion of Sirt6 in mice promoted diet-induced obesity and insulin resistance." (PMID 29535637, 2018). "SIRT6 protected against insulin resistance and obesity induced by HFD." (PMID 30559718, 2018). "Recent studies have suggested that reduced Sirt6 action is related to obesity and diabetes." (PMID 29535637, 2018). "Recent studies have suggested reduced Sirt6 activity related to obesity and diabetes." (PMID 29535637, 2018). "This review summarizes the role of Sirt6 in obesity and diabetes." (PMID 29535637, 2018). "Sirt6 transgenic mice exhibit resistance to HFD-induced obesity and insulin resistance." (PMID 30574122, 2018). "In contrast, Sirt6 overexpression protected against diet-induced obesity and insulin resistance." (PMID 29535637, 2018). "In this regard, the nucleus-specific Sirt6 level is involved in obesity and diabetes." (PMID 30671172, 2018). "Therefore, our study indicates a biological function of SIRT6 in adipogenesis and provides potential therapeutic targets for obesity." (PMID 28355567, 2017).
Obesity (continued). "Also, it was shown that SIRT6-deficient mice have a premature aging phenotype with a shortened lifespan, while the overexpression of SIRT6 prolongs the lifespan in male mice and prevents diet-induced obesity." (PMID 28635654, 2017). "However, this is in contrast to other mouse models with neural deletion of Sirt6, which leads to early growth retardation and obesity, while overexpression of Sirt6 in different models extends lifespan and protects against diet-induced obesity." (PMID 27763519, 2016). "Regarding the physiological role of H3K56 acetylation, recent work in Sirt6 knock-out mice reveals the association between hyperacetylation of H3K56 and obesity: neural specific Sirt6-deleted mice have adult-onset obesity, and they show hyperacetylation at H3K9 and H3K56 in various brain regions." (PMID 21655096, 2011). "Notably, we have found that Sirt6-LKO mice exhibit the spontaneous development of liver tumors at approximately two years of age, while also being susceptible to tumor formation induced by diethylnitrosamine (DEN) treatment or ob/ob related obesity." (PMID 38332150, 2024). "However, the exact mechanism for microglia Sirt6 in controlling high-fat diet-induced obesity remain unknown." (PMID 37582706, 2023). "Thus, hepatic SIRT6 likely inhibits diet-induced obesity by suppressing hepatic CYP7A1." (PMID 37566087, 2023). "Thus, hepatic SIRT6 is required to prevent diet-induced obesity by regulating energy expenditure." (PMID 37566087, 2023). "However, deletion of SIRT6 in the adipose tissue markedly impairs the function of thermogenesis of BAT, causing substantial “whitening” of BAT in mice, while mice's oxygen consumption rate and body temperature decrease, leading to obesity." (PMID 33274005, 2020). "Research indicates that theaflavins TF1, TF2a, and TF3 enhance glucose and lipid metabolism in mice on a HFD by activating the SIRT6/AMPK/SREBP-1/FASN pathway, thus effectively mitigating obesity symptoms." (PMID 39606571, 2024). "On the contrary, adipose tissue-specific deletion of SIRT6 sensitized mice to HFD obesity and led to a decreased adipose triglyceride lipase (ATGL) levels due to acetylation changes on its transcriptional regulator, FOXO1 in the SIRT6 KO mice." (PMID 39109269, 2024). "In conclusion, our data indicate that hepatocyte SIRT6 protects against atherosclerosis, NAFLD, and obesity by regulating lipid metabolism in the liver and intestine." (PMID 37566087, 2023). "Therefore, microglial Sirt6 may be an important therapeutic target for obesity." (PMID 37582706, 2023). "Thus, microglial Sirt6 may be an important therapeutic target for obesity." (PMID 37582706, 2023). "The role of hepatic SIRT6 in the development of nonalcoholic steatohepatitis (NASH), atherosclerosis, and obesity was investigated." (PMID 37566087, 2023). "Mounting studies have believed that SIRT6 protected cells in many diseases including NAFLD, T2DM, and obesity based on IR." (PMID 34745416, 2021). "The genes that formed the negative regulation of the glucose import category (PEA15, SIRT6, LEP, and VIMP), were related to obesity and diabetes in human." (PMID 33850161, 2021). "Collectively, these data indicate that adipocyte Sirt6 enhances oxidative capacity and thermogenesis and is necessary for the benefits of IF—protection against HFD-induced obesity and insulin resistance—to accrue to mice." (PMID 34493807, 2021). "In conclusion, this study demonstrated that chrysophanol can activate brown fat through the SIRT6/AMPK pathway and increase energy consumption, insulin sensitivity, and heat production, thereby alleviating obesity and metabolic disorders." (PMID 33274005, 2020).
Obesity (continued). "Conversely, fat-specific Sirt6 knockout increases blood glucose levels and hepatic steatosis, and sensitizes mice to HFD-induced obesity and insulin resistance." (PMID 30574122, 2018). "Oxidative stress in obesity is a systematic problem that can be reduced by improving antioxidant defenses through fat reduction, physical activity or exercise, dietary restriction, surgical intervention, or antioxidant therapies which, based on the results showed in this work, may include SIRT6." (PMID 30671172, 2018). "Sirt6 depletion reduced phosphorylated ATF2 binding to the PGC-1α promoter and subsequently decreased the thermogenic program of brown fat and led to obesity." (PMID 29535637, 2018). "In adipose tissue, Sirt6 deletion moderates the binding of phosphorylated ATF2 to the PGC-1α promoter, which subsequently reduces the thermogenic programme in brown fat and eventually leads to obesity." (PMID 37582706, 2023). "In this study, we used mice over-expressing or lacking hepatic SIRT6 to show that hepatic SIRT6 protects against Western diet-induced atherosclerosis, steatohepatitis, and obesity." (PMID 37566087, 2023). "In summary, we identified hepatic SIRT6 as a key regulator of NAFLD, atherosclerosis, and obesity." (PMID 37566087, 2023). "Despite significant research conducted on the role of hepatic SIRT6 in metabolic regulation, the role of hepatic SIRT6 in atherosclerosis or obesity has not been explored." (PMID 37566087, 2023). "Currently, the role of Sirt6 in diet-induced obesity-related hypothalamic inflammation has not been reported." (PMID 37582706, 2023). "SIRT6 is also highly expressed in the CNS, and its expression is regulated by the availability of nutrients, showing low levels in the hypothalamus and specifically in POMC neurons in obesity." (PMID 33572672, 2021). "In addition, given thecentral role that SIRT6 plays in processes such as DNA repair, metabolism,aging, and tumorigenesis, small-molecule modulators could representpotential weapons for SIRT6-targeted treatment of diseases such asdiabetes, obesity, cancer, and neurodegeneration." (PMID 34213345, 2021). "SIRT6 deletion results in hyperacetylation of histones H3K9 and H3K56, suggesting that histone deacetylase activity of SIRT6 may play a role in managing obesity in rats." (PMID 33806509, 2021). "Moreover, the drug T1AM increases SIRT6 levels, whereas it decreases SIRT4 levels, as well as reversing obesity through metabolic reprogramming." (PMID 33806509, 2021). "Sirt6 ablation increased diet-induced obesity via adipocyte hypertrophy rather than abnormal adipocyte differentiation." (PMID 29535637, 2018). "Sirt6 ablation mediated by ap2-CRE or adiponectin-CRE in adipose tissue increased HFD-induced obesity and insulin resistance, and Sirt6 overexpression inhibited HFD-induced obesity and insulin resistance." (PMID 29535637, 2018). "In a recent study we showed that over-expression of SIRT6 extends lifespan of male mice, and protects against high-fat-diet-induced obesity, although we still do not fully understand the exact mechanism by which SIRT6 operates." (PMID 25428368, 2015). "Importantly, there was a negative correlation between the extent of obesity or insulin resistance and SIRT6 levels in human visceral fat tissues." (PMID 38016059, 2023). "Although SIRT6 has been shown to regulate obesity, it has not been investigated whether hepatic SIRT6 regulates obesity." (PMID 37566087, 2023). "The role of hepatic SIRT6 in atherosclerosis or obesity has not been investigated before." (PMID 37566087, 2023). "As an example, lack of SIRT1-, SIRT2-, and SIRT6-dependent deacetylation and activation of specific adipose gene programs was shown to contribute to the development of metabolic disorders, such as type 2 diabetes and obesity." (PMID 34829720, 2021).